INS (insulin)
Diseases named in the same sentence as INS in open-access papers (continued):
Sharing a sentence is not in itself a finding about the gene and the disease.
anxiety disorder (7 papers, 2018 to 2023). A category of psychiatric disorders which are characterized by anxious feelings or fear often accompanied by physical symptoms associated with anxiety. "For instance, ELS induces persistent increases in insulin resistance, hippocampal and corpus callosum atrophy and reduced “behavioral plasticity”, which, taken together, engenders an increased risk for mood and anxiety disorders in humans but also a putative sparing of calories." (PMID 29888314, 2018).
bulimia nervosa (7 papers, 2019 to 2025). A disorder characterized by recurrent episodes of binge-eating over which the individual feels a lack of control; these episodes of binge-eating are followed by recurrent compensatory behavior to prevent weight gain, usually self-induced vomiting. "Therefore, high levels of insulin will be seen often in women who suffer from bulimia nervosa as a consequence of binge eating, characterized as eating huge quantities of usually unhealthy, processed food." (PMID 39797110, 2024). "Combining the facts that women with bulimia nervosa or binge eating have high glucose levels due to compulsive eating, if they additionally have PCOS and high serum kisspeptin levels, a synergistic effect is created in them, leading to insulin resistance, which is part of the pathogenesis of PCOS." (PMID 39797110, 2024).
cerebral small vessel disease (7 papers, 2013 to 2026). Cerebral small vessel disease is the term currently used to pathological processes that affect the brain parenchymal circulation (arterioles, capillaries, and veins). "Both insulin sensitivity and brain glymphatic function were linked to cognitive function in nondiabetic patients with cerebral small vessel disease (CSVD)." (PMID 41431341, 2025). "The highest impact on glucose uptake is shown by insulin-independent GLUT1 and GLUT3, although insulin-dependent GLUT4 is also important, having a key role in vascular diseases, including DM-related cerebral small vessel diseases." (PMID 36834741, 2023).
chronic lung disease (7 papers, 2017 to 2025). According to the definitions of the American and British Thoracic Societies, including pulmonary functional tests, X-rays, and CT scans for items such as fibrosis, bronchiectasis, bullae, emphysema, nodular or lymphomatous abnormalities. "Several very small studies in patients with chronic lung disease indicate that treatment with oral hypoglycaemics and/or insulin can reduce exacerbation rate and alter sputum microbiology." (PMID 28192604, 2017).
developmental delay (7 papers, 2011 to 2025). "Despite advances in genetic diagnosis, the management of pancreatic agenesis remains challenging due to the lifelong need for insulin and pancreatic enzyme replacement, as well as the high risk of complications such as recurrent infections, metabolic instability, and developmental delays." (PMID 41393705, 2025). "A 2019 review of PDX1-related agenesis cases found that 60% of patients required lifelong insulin and enzyme therapy, with developmental delays noted in 40%." (PMID 41393705, 2025). "If viewed as a developmental delay, the fetal deregulation of insulin production and signaling might be assumed as becoming compensated later in life." (PMID 31750562, 2020).
diabetic macular edema (7 papers, 2013 to 2026). "A recent retrospective cohort analysis revealed that, compared to the combination of SGLT-2 inhibitors with insulin, the concomitant use of GLP-1RAs and insulin was associated with a significantly elevated risk of DR and diabetic macular edema." (PMID 41501669, 2026). "Although metformin was weakly correlated with downregulation of hypoxia-inducible factor-1α/VEGF induced by insulin and insulin-like growth factor, this effect was insufficient to control the symptomatic diabetic macular edema." (PMID 29854819, 2018).
herpes simplex infection (7 papers, 2017 to 2025). "These genes were all annotated to the neuroactive ligand–receptor interaction, regulation of actin cytoskeleton, endocytosis, herpes simplex infection, tight junction, insulin signaling pathway and melanogenesis, and some of the pathways were associated with infection and immunity." (PMID 38003649, 2023).
homeostasis (7 papers, 2020 to 2025). "Plasma glucose and insulin are commonly measured clinically but are less sensitive to detect impaired glucose homeostasis compared with insulin and glucose tolerance tests." (PMID 32698498, 2020). "As the sensitivity of peripheral tissues to insulin signaling continues to decline, the body gradually shows manifestations of glucose homeostasis disorders such as elevated fasting blood glucose and abnormal glucose tolerance, ultimately forming a systemic insulin resistance state." (PMID 41450839, 2025).
hyperaldosteronism (7 papers, 2018 to 2023). Overproduction of aldosterone by the adrenal glands, which may lead to hypokalemia and/or hypernatremia. "In this context, we have found that aldosterone negatively affects insulin and β1AR function both in vitro in 3T3 cells and in vivo in the hearts of two murine models of hyperaldosteronism (aldosterone-infused or infarcted mice)." (PMID 31447681, 2019).
kidney transplant (7 papers, 2013 to 2025). A surgical procedure in which one or both kidneys from a donor are implanted into a recipient. "An earlier study in kidney transplant recipients showed a relatively poor correlation between these quantifications and insulin sensitivity index measured with a euglycemic-hyperinsulinemic glucose clamp with Spearman’s correlations of 0.41 and 0.58, respectively." (PMID 39911868, 2025). "Even though prednisolone is a risk factor for PTDM, one study in kidney transplant recipients demonstrated that patients who use prednisolone in a daily dosage of 5 mg or lower had no improvement in insulin sensitivity (assessed with glucose clamp technique)." (PMID 35516977, 2022).
lymph node metastasis (7 papers, 2017 to 2025). "However, there have been little data on the association between insulin levels and the risk of lymph node metastasis." (PMID 29533014, 2018).
metastatic cancer (7 papers, 2015 to 2025). A carcinoma which has spread from the original site of growth to another anatomic site. "Maintaining total caloric intake to prevent weight loss while improving systemic insulin levels, metabolic factors, and hormone levels is likely to promote safer implementation, increased adherence, and potentially improvement of metastatic cancer outcomes." (PMID 36079800, 2022). "Accordingly, elevated levels of circulating insulin have been associated with an increased cancer risk as well as with aggressive and metastatic cancer phenotypes." (PMID 25798130, 2015). "This dichotomy extends to molecular mechanisms, where epigenetic reprogramming of immune cells and plasma metabolome modifications correlate with improved insulin sensitivity, yet cachexia progression remains unaffected in metastatic cancer models." (PMID 40160324, 2025). "In this narrative review, we searched the published literature for studies that tested various insulin-lowering diets in metastatic cancer in preclinical and clinical settings." (PMID 36079800, 2022). "We present preliminary clinical studies that address feasibility and implementation of insulin-lowering diets in patients with metastatic cancer and the potential impact of these diets on cancer outcomes." (PMID 36079800, 2022). "Summary of preclinical studies testing insulin-lowering dietary strategies in models of metastatic cancer." (PMID 36079800, 2022). "Several questions remain to be answered: Do insulin-lowering strategies ultimately improve outcomes and prolong survival in patients with metastatic cancer?" (PMID 36079800, 2022). "Finally, we discuss ongoing and future clinical trials and provide recommendations for best practices in designing trials utilizing insulin-lowering dietary strategies in patients with metastatic cancer." (PMID 36079800, 2022). "Acquired resistance to leptin and/or insulin is likely to interfere with this signaling and increase the risk of metastatic cancer; the lack of reaction of DLD-1 cells to leptin in our study illustrates such dysfunction on the cellular level." (PMID 27842582, 2016).
myotonic dystrophy type 1 (7 papers, 2015 to 2025). Steinert disease, also known as myotonic dystrophy type 1, is a muscle disease characterized by myotonia and by multiorgan damage that combines various degrees of muscle weakness, arrhythmia and/or cardiac conduction disorders, cataract, endocrine damage, sleep disorders and baldness. "In this review, we have consolidated the clinical and molecular evidence for the involvement of insulin signaling in myotonic dystrophy type 1." (PMID 31849810, 2019). "In addition, myomesin has been associated with myotonic dystrophy type 1 (DM1), a multisystem disease characterized by myotonia, muscle weakness, cardiac conduction defects, insulin resistance, and mental retardation." (PMID 25961035, 2015). "This phenomenon is also observed in individuals with myotonic dystrophy type 1, who have overexpression of INSRA isoform and a poor metabolic response to insulin." (PMID 25742416, 2015). "Another example involves Myotonic Dystrophy type 1 (DM1; OMIM #160900), an autosomal dominant inherited disease affecting multiple tissues with symptoms that span from myotonia, progressive muscle wasting, cardiac arrhythmias to insulin resistance." (PMID 28146073, 2017).
primary hyperparathyroidism (7 papers, 2014 to 2026). "Therefore, the role of OC in the circulatory levels of insulin as a causative or concomitant factor in primary hyperparathyroidism still needs to be determined." (PMID 27626477, 2016). "Despite the increased serum levels of osteocalcin due to primary hyperparathyroidism, these patients tend to have impaired insulin sensitivity." (PMID 27626477, 2016). "While insulin may be increased during primary hyperparathyroidism, it is noted that patients are likely to be paradoxically resistant." (PMID 37350980, 2023). "In addition, elevated serum Ca levels in patients with primary hyperparathyroidism may affect insulin secretion." (PMID 35698198, 2022).
retinal degeneration (7 papers, 2020 to 2025). Degeneration of the retina. "Understanding this extra-pancreatic insulin source opens new therapeutic perspectives aimed at enhancing local insulin signaling to preserve vision and prevent retinal degeneration." (PMID 41301488, 2025). "The stimulation of glucose uptake in cones by rod-derived cone viability factor or insulin has been shown to rescue cones in a model of retinal degeneration." (PMID 31900165, 2020). "Our results indicate that insulin signaling promotes cone survival in retinal explants confirming previous results in a mouse retinal degeneration model." (PMID 33243251, 2020). "Our results showed that all the insulin signaling pathway genes are downregulated in the mutant zebrafish and may be involved in the retinal degeneration mechanism." (PMID 32033529, 2020). "Finally, our results further connect several metabolic pathways with retinal degeneration, including insulin, mTOR, and HIF-1 signaling, which in future studies may help to understand the complex mechanisms behind photoreceptor cell death." (PMID 35241647, 2022). "We show that pharmacological stimulation of INSR signaling with Pi has a disease-modifying effect over the course of retinal degeneration, in line with the beneficial effects of INSR stimulation with insulin reported in other neurodegenerative diseases of the brain and retina." (PMID 35444190, 2022).
rhabdomyolysis (7 papers, 2016 to 2025). Necrosis or disintegration of skeletal muscle often followed by myoglobinuria. "Elevated glycogen stores in connection with insulin sensitivity has been suggested to be connected to exercise‐induced rhabdomyolysis in PSSM horses, although the mechanisms are unclear." (PMID 40329464, 2025). "We postulate that the later episodes of rhabdomyolysis occurred because of a progressive decrease in insulin production with a consequent reduction in the uptake of blood glucose by muscle cells, thus compromising the cellular energy balance." (PMID 33153458, 2020). "Medians and ranges for selected cytokines, CRP, insulin and cortisol before (day 0) and after successfully completing day 4 of the 2015 Yukon Quest and 5 dogs with exertional rhabdomyolysis (ER)." (PMID 30073172, 2018). "The remaining 2 drugs involved (lorazepam and rapid insulin) do not mention rhabdomyolysis as an adverse effect, but this is explained by the much lower frequency of these adverse reactions in these cases." (PMID 35873584, 2022). "We think that the administration of insulin is very unlikely to be one of the reasons for the rhabdomyolysis." (PMID 27442680, 2016).
sarcoma (7 papers, 1971 to 2025). A usually aggressive malignant neoplasm of the soft tissue or bone. "In STLMS, reduced signaling from tumor necrosis factor (TNF) in the adipocytokine signaling pathway leads to elevated activation of IRS, involved in insulin sensitivity, whose expression has been related to malignant sarcoma progression." (PMID 37834179, 2023). "Vulval sarcomas are usually rare but are increased in numbers in diabetic and in insulin treated intacts." (PMID 4335634, 1971). "Thus, the activation of the hedgehog signaling pathway, previously reported in sarcoma patients, would promote a dedifferentiated morphology of adipocytes, decreased lipid accumulation, and insulin resistance." (PMID 37834179, 2023). "In particular, although feline injection site sarcomas are believed to be exceedingly rare and have not been linked to daily insulin injections or to microchip implants, this risk will need to be ruled out for the OKV-119 implantable system." (PMID 34046446, 2021). "These desirable features are particularly interesting for pediatric sarcomas, a group of rare tumors that have been shown to be dependent on IGF and insulin system for pathogenesis and progression." (PMID 24391834, 2013).
skin cancer (7 papers, 2016 to 2026). "However, it is safe to say that Resv prevents the development of coronary vascular disease, improves insulin sensitivity, reduces serum glucose, and prevents the development of cancers of the skin, colon, and prostate in animal models." (PMID 27294953, 2016).
somatostatinoma (7 papers, 2017 to 2023). A rare, usually malignant neuroendocrine tumor arizing from delta cells. "In most patients (92.7%), the clinical somatostatinoma syndrome was caused by the inhibition of insulin, glucagon, gastrin, secretin, and somatotrophin." (PMID 33204258, 2020). "Co‐secretion of insulin (in addition to somatostatin) by the hepatic somatostatinoma was well characterized as mechanism of hypoglycaemia in this patient." (PMID 31592116, 2019).
urolithiasis (7 papers, 2017 to 2025). Stone(s) within the urinary tract. "Based on our results, the highest odds of having urinary stones were seen in those with poor glycemic control and high insulin resistance." (PMID 38021767, 2023). "An interesting observation of this work is the fact that both of the tested high-fructose diets, given for an 8-week period, based on a liquid 10% FR solution or a solid 60% FR feed, were able to induce urolithiasis in rats characterized by high insulin level and hypercalciuria." (PMID 35008629, 2021).
urticaria (7 papers, 2005 to 2024). A vascular reaction of the skin characterized by erythema and wheal formation due to localized increase of vascular permeability. "The increased incidence of urticaria in children with T1DM might be caused by insulin injections." (PMID 31881760, 2019). "During the first weeks of December 2012, the mother started to notice small urticaria lesions on her son's legs and torso 2 hours after insulin injection, which disappeared with the use of common oral antihistamines such as Loratadine." (PMID 25548690, 2014). "Examination after bolus of Human Insulin revealed urticaria." (PMID 16375762, 2005). "Urticaria was an insulin non-initiation risk factor with a high effect size." (PMID 32408626, 2020). "Since SIRT1 is a key regulatory factor in the regulation of glucose metabolism and insulin secretion, researchers have observed that SIRT1 can participate in the disorder of glucose metabolism in the skin tissue of urticaria mice, and up-regulation of SIRT1 can increase insulin secretion." (PMID 39081309, 2024).
Uterine leiomyoma (7 papers, 2014 to 2025). The presence of a leiomyoma of the uterus. "In premenopausal women with symptomatic uterine leiomyomas, GnRH agonists also increased insulin levels and HOMA scores." (PMID 24912407, 2014). "Additionally, some studies have found an inverse correlation between diabetes and uterine leiomyoma, and other researchers hypothesize that insulin stimulates fibroid growth." (PMID 37576957, 2023). "Furthermore, inositol is essential for the regulation of insulin and estrogen and is frequently used to treat polycystic ovarian syndrome (PCOS), a condition that has characteristics with uterine leiomyomas in terms of hormonal disturbance." (PMID 41459082, 2025). "There was no ketosis at diagnosis, but insulin therapy was required because of the preoperative condition for uterine fibroids." (PMID 39247010, 2024).
adrenal hypoplasia (6 papers, 2016 to 2025). "Since insulin directly affects testicular steroidogenesis via the induction of dosage-sensitive sex reversal, adrenal hypoplasia critical region, on chromosome X, gene 1 (DAX-1) in Leydig cells, it possible that GnIH may inhibit steroidogenesis by downregulating IR in the testis." (PMID 26869993, 2016).
airway hyperresponsiveness (6 papers, 2023 to 2025). "In vitro and animal studies have shown that increased insulin levels are associated with higher bronchial smooth muscle proliferation and airway hyperresponsiveness." (PMID 37056543, 2023). "Furthermore, it has been demonstrated that insulin directly causes airway hyperresponsiveness and fibroblast collagen deposition." (PMID 40421215, 2025). "Thus, high levels of insulin cause airway hyperresponsiveness via affecting both sensory and parasympathetic nerves." (PMID 39782687, 2025). "High-fat diets also increase circulating insulin in rats and mice and insulin potentiates nerve-mediated airway hyperresponsiveness." (PMID 39316677, 2024). "Here, we show a beneficial effect of eosinophils in adipose tissue reduces circulating insulin and reverses nerve-mediated airway hyperresponsiveness in obese mice." (PMID 39316677, 2024). "Insulin sensitizer drugs alleviated airway hyperresponsiveness (AHR) in an obese, asthmatic animal model, suggesting that insulin resistance can play a critical role in bronchial reactivity." (PMID 37108123, 2023). "+IL-5T mice, with increased circulating eosinophils, on high-fat diet had low levels of fasting insulin and did not have airway hyperresponsiveness." (PMID 39316677, 2024). "Although wild-type mice on a high-fat diet developed increased insulin and airway hyperresponsiveness, +IL-5T mice fed a high-fat diet did not develop either increased insulin or airway hyperresponsiveness." (PMID 39316677, 2024).
Ascites (6 papers, 2010 to 2025). Accumulation of fluid in the peritoneal cavity (between the layers of the peritoneum that lines the abdomen). "Among patients with baseline ascites, 20 of 20 patients in the SGLT2i group experienced complete resolution of ascites by 48 months compared to 11 of 17 patients in the insulin group (p = 0.03)." (PMID 40444235, 2025).